S100A8 (S100 calcium binding protein A8)
Diseases named in the same sentence as S100A8 in open-access papers (continued):
Sharing a sentence is not in itself a finding about the gene and the disease.
cancer (continued). "From these data, we selected potential biomarkers of cancer including six upregulated proteins (RNF213, CTSG, PGLYRP1, RPL8, S100A8, S100A9) and two downregulated proteins (GPX1, TNS1)." (PMID 34361002, 2021). "Conversely, S100A8/A9 binding decreases at CTCF motifs during transformation, and CTCF haploinsufficiency in mice leads to increased cancer incidence." (PMID 33523865, 2021). "DNA hypomethylation also contributes to the regulation of the expression of S100A6, S100A8 and S100A11 in various cancers." (PMID 33466593, 2021). "Another therapeutic potential of targeting NETosis is connected to the ability of NETs to secrete the Ca2+-binding proteins S100A8 and S100A9, which are considered key players in linking inflammation and cancer." (PMID 34201758, 2021). "Notably, 67% of annotated cancer genes are associated with S100A8/A9 target genes, in comparison to only 55% of noncancer genes, which is highly significant (P < 2.2 × 10−16; Fisher’s exact test) with contributions from ONG (P = 2 × 10−8), TSG (P = 2 × 10−14), and OncoTSG enrichment (P = 6 × 10−6)." (PMID 33523865, 2021). "Because most of the S100 proteins have been considered as EMT facilitators in certain carcinoma cell lines, the present study showed that HE of AHNAK2 had a significantly higher proportion of S100A4, S100A8, and S100A9 expressions." (PMID 33918555, 2021). "Besides that, S100A8/A9 can enhance the immunosuppressive activity and regulate the accumulation of MDSCs at the site of inflammation, indicating that such proteins could play a major role in the pathogenesis of cancer, or at least certain cancer types." (PMID 32931721, 2020). "S100A8 and S100A9 function as essential factors in inflammation and also exert antitumor or tumorigenic activity depending on the type of cancer." (PMID 32903598, 2020). "Like S100A8/A9, LGALS3BP is expressed in a number of human cancer entities, though its putative oncogenic role is only poorly understood." (PMID 32503348, 2020). "S100A8 and S100A9, two heterodimer-forming members of the S100 family, aberrantly express in a variety of cancer types." (PMID 31208368, 2019). "Infiltrating monocytes/macrophages lead to upregulation of S100A8 and S100A9 expression in cancer cells, which was correlated with elevated metastasis formation in HCC." (PMID 31611871, 2019). "It has reported that S100A8/S100A9 forms heterodimers and plays an important role in regulating cells proliferation and apoptosis in some normal and cancer cells." (PMID 31208368, 2019). "For example, the over-expression of S100A2, S100A3, S100A6, S100A8/A9, S100A11 and S100A14 have been documented in several cancer types." (PMID 30018736, 2018). "S100A8-GST and S100A9-GST were incubated with anti-S100A8 and anti-S100A9 neutralising antibodies for 1 h before addition to cancer cell cultures." (PMID 30558665, 2018). "Recent studies have highlighted S100A8 and S100A9 as having an important role in cancer pathogenesis." (PMID 29955397, 2018). "S100A8-GST and S100A9-GST were incubated with respective neutralizing antibodies (anti-S100A8 and anti-S100A9) for 1 h at 37 °C before addition to cancer cells." (PMID 30558665, 2018). "Calprotectin, a heterodimeric complex of the calcium-binding proteins S100A8 and S100A9, regulates cell cycle progression at G2/M, inhibiting cancer cell migration and invasion, and suppressing tumorigenesis in vitro and in vivo." (PMID 29868478, 2018). "Strong up-regulation of S100A8/S100A9 has also been detected in various human cancers and promotes tumors progression, including gastric, colon, breast, and live cancer." (PMID 30558666, 2018). "S100A8/9, correlated with PCa progression, can regulate MDSC expansion and also trigger the NFκB pathway in cancer cells to promote proliferation and migration." (PMID 29142311, 2017).
cancer (continued). "In contrast, some of past studies showed that S100A8 and S100A9 protein have inhibitory effects on the proliferation of carcinoma cells and normal fibroblasts by inducing cell apoptosis." (PMID 28637501, 2017). "Downregulation of S100A8 and S100A9 was further accompanied by decreased MMP2 and MMP9 expression in cancer cells, both in culture and in metastatic liver colonies." (PMID 27086923, 2016). "Suppression of S100A8 and S100A9 in cancer cells using short hairpin RNA significantly diminished migration and invasion in culture." (PMID 27086923, 2016). "In the same study, we also found that S100A8 and S100A9 expression in cancer cells was altered by removal of the CD11b+ cells." (PMID 27086923, 2016). "Decrease in calcium levels upon stimulation was abrogated when S100A8 and S100A9 were knocked down in the cancer cells." (PMID 27086923, 2016). "S100A8 and S100A9 knockdown significantly decreased MMP2 and MMP9 protein levels in the cancer cells." (PMID 27086923, 2016). "In this report, however, we do explain how expression of S100A8/A9 is likely controlled in HNSCC and how the cancer phenotype is affected." (PMID 26883112, 2016). "Because the levels of S100A8 and S100A9 in untreated MC38 and LLC cells were low, we first induced S100A8 and S100A9 expression by stimulating cancer cells with monocyte/macrophage-conditioned medium." (PMID 27086923, 2016). "The reason for choosing midostaurin, enzastaurin, and gefitinib as inhibitor for S100A8 and EGFR is the recent research showing that EGFR-targeted therapies using kinase inhibitors are effective in many cancer patients." (PMID 25789858, 2015). "S100A8 and EGFR do play an important role in malignancy and thus considered as potential drug targets for cancer therapeutics development." (PMID 25789858, 2015). "S100A8 and S100A9 were upregulated in RCC patients compared with patients with benign kidney lesions, other urological tumors or non-cancer patients." (PMID 25673070, 2015). "It indicates that there is a direct link between the expression of IL-17, CCL20, telomerase, S100A8, and S100A9 in the fibrotic condition and the progression towards cancer." (PMID 26273651, 2015). "The S100A8 and epidermal growth factor receptor (EGFR) proteins are proto-oncogenes that are strongly expressed in a number of cancer types." (PMID 25789858, 2015). "For example, over-expression of S100A2, S100A3, S100A6, S100A8/A9, and S100A11 is related to several types of cancer, whereas other types of cancer are characterized by the under-expression of these same proteins." (PMID 25988147, 2014). "Abnormal expressions of S100 proteins, including S100A8 and S100A9, were over-expressed in a variety of different cancers, such as gastric, lung, breast, liver, pancreatic and squamous esophageal carcinomas." (PMID 23637971, 2013). "An increasing amount of data indicate that S100A8 as well as S100A9 homodimers are important regulators of inflammation and cancer, exhibiting strong pro-inflammatory activity in various mouse models of diseases." (PMID 23626736, 2013). "In this study, we found that S100A8/A9 functions as a negative regulator of cell division and growth in KB and TR146 human carcinoma cells by inducing G2/M cell cycle arrest." (PMID 23874958, 2013). "S100A8 and S100A9 proteins, usually occurring as the heterodimeric complex, calprotectin, are changed significantly at the early stages of cancer." (PMID 23166536, 2012). "S100A8 and S100A9 are often co-expressed as a complex, suggesting a common mechanism of transcriptional regulation in inflammatory diseases and cancers." (PMID 22139384, 2012). "We focused our study on S100A8 and its heterodimeric partner S100A9 because of their role in inflammation and cancer, and their prominence among ZD-induced proinflammation markers in ZD:Cox-2−/− forestomach." (PMID 20857495, 2011).
cancer (continued). "Increased levels of S100A8 and S100A9 have been detected in various human cancers, being abundantly expressed in neoplastic cells and also in infiltrating immune cells." (PMID 19440546, 2009). "We also discovered Syntaphilin (SNPH) as an S100A8/A9-dependent gene enriched specifically in estrogen receptor-negative (ER-) cancers from former smokers, linking this response to patient disease." (PMID 39856330, 2025). "The livers of TRPV4-KO mice exhibited fewer cancer cell microlesions, lacked macrotumors, produced lower levels of inflammatory protein S100A8, and developed fewer inflammatory cell clusters." (PMID 41100488, 2025). "S100a8 and S100a9, secreted by adipocytes, preadipocytes, or neutrophils, have been identified as key genes affecting lipid metabolism, such as FFA (18:3), and in turn, cancer development in aged animals." (PMID 39796176, 2025). "Some of these potential proteins (COL12A1, THBS2, S100A8, and S100A9) were reported to associate with other cancers and non-malignant diseases, which limited the clinical validity of the potential proteins in CRC." (PMID 38302471, 2024). "S100A8 and S100A9/Cd93 were major communication axes within Cancer-B1/2/3-TME." (PMID 39695088, 2024). "We also explored the predictive efficacy of the four proteins (COL12A1, THBS2, S100A8, and S100A9) in multi-cancer cohort composed of 115 plasma samples from 95 patients with treatment-naive patients with various cancer types and 20 HCs, and two public cohorts related to the non-malignant diseases." (PMID 38302471, 2024). "Blocking the effect of S100A8 and/or S100A9 in cancer-related inflammation could potentially relieve myeloid-mediated immune suppression and synergize with other cancer immunotherapies." (PMID 39497822, 2024). "Similarly, the GDS4382 dataset showed significantly higher expression of S100A8 and S100A9 in cancer tissues compared to corresponding paracancerous tissues (P<0.05)." (PMID 38817853, 2024). "Additionally, S100A8 and S100A9 are considered biomarkers of poor prognosis in inflammatory and metabolic diseases as well as some types of cancer." (PMID 38049858, 2023). "S100A8/A9 and HMGB1 are potential biomarkers for the accumulation of MDSCs and their neutralization and/or the inhibition of RAGE may enhance cancer immunotherapies." (PMID 36831371, 2023). "Accumulating evidence suggests that S100A8 targeting can be therapeutically useful in advanced cancers, however there is no such treatment for S100A8 targeting." (PMID 36932197, 2023). "Additionally, miR193a-CM upregulated genes for S100A8, AKR1C1, AREG, and PLIN2 were shown to inhibit angiogenesis and cancer growth." (PMID 36766731, 2023). "Also, S100A8 and S100A9 were down-regulated after CD36 knockdown, which are classical ligands related to cancer aggressiveness." (PMID 37207149, 2023). "S100A8 did not affect the percentage or absolute numbers of CD8 T cells in lungs or spleens from cancer-bearing mice, although it reduced total T cell and DNT cell infiltration in lungs from control mice (p < 0.05)." (PMID 35655772, 2022). "Percentages of MDSC populations in bone marrow or lymph nodes were not affected by S100A8 in mice with LLC cancers." (PMID 35655772, 2022). "Concurrently, S100A8 significantly decreased protein levels of IL-4 (381.0 ± 66.6 pg/mL to 194.3 ± 34.2 pg/mL, p < 0.05) and IFN-γ (121.5 ± 16.5 pg/mL to 22.1 ± 5.5 pg/mL, p < 0.0001) in BALF from mice with LLC cancers to basal levels." (PMID 35655772, 2022). "Given the multiple molecules that interact with HRG, HRG-mediated cancer prevention in vivo would not be attributable to the prevention of S100A8/A9 activities alone." (PMID 36142212, 2022). "S100A8 markedly induced expression of several redox genes on Day 10, including superoxide dismutase (SOD1) (5.8 x 105 fold, p < 0.01) and thioredoxin (TXN) (1.5 x 105 fold, p < 0.05) in lungs of mice with LLC cancers." (PMID 35655772, 2022).
cancer (continued). "Next, to evaluate the significance of HRG binding to S100A8/A9, we used cancer cells in culture with the purified S100A8/A9 recombinant protein in the presence or absence of HRG in the extracellular space." (PMID 36142212, 2022). "A heterodimer complex of the S100A8 and S100A9 proteins, S100A8/A9 functions as a strong chemoattractant, growth factor, and immune suppressor, both promoting the cancer milieu at the cancer-onset site and cultivating remote, premetastatic cancer sites." (PMID 36142212, 2022). "Lately, S100A8 and S100A9 have been increasingly used as in vivo imaging biomarkers in cancer." (PMID 35741108, 2022). "Surprisingly, however, there have been no reports on HRG’s interaction with S100A8/A9 or on the relevance of HRG to S100A8/A9-mediated cancer biology." (PMID 36142212, 2022). "Regardless of the source, S100A8/A9 appears to play essential roles in both inflammation-induced cancer and cancer-induced inflammation and mediate concentration-dependent protumor response." (PMID 35610567, 2022). "On the other hand, another type of neutrophils called N2 neutrophils appear to be tightly involved in cancer progression through the active formation of neutrophil extracellular traps (NETs), which release abundant HMGB1 extracellularly as well as S100A8/A9 and our unpublished data." (PMID 36142212, 2022). "In addition, inflammatory and angiogenic factors, including S100A8 and VEGF were also increased in the lungs of cancer-bearing MMTV-PyVT mice, compared with wild-type mice." (PMID 36612175, 2022). "Based on how effective HRG is against S100A8/A9, HRG may lead to an effective therapy to prevent the progression of several types of cancers." (PMID 36142212, 2022). "In addition, accumulating research showed that MDSCs have potent mechanisms to promote cancer growth (via downregulation of IFN-γ and expression of MMP9) and metastasis (via TNFα, TGFβ, CXCL2 and S100A8/9) by establishing an immunotolerant environment." (PMID 35211124, 2022). "Similarly, S100A8 significantly reduced percentages of total and M-MDSC in spleens from mice with LLC cancers (Total MDSC: 1.10 ± 0.15% to 0.62 ± 0.10%, p < 0.05; M-MDSC: 0.18 ± 0.04% to 0.07 ± 0.01%, p < 0.05); PMN-MDSC showed a trend of decrease." (PMID 35655772, 2022). "To date, S100A8 expression, or overexpression of TLR4, was observed in various cancers." (PMID 35780158, 2022). "Proteins S100A8, S100A9, or hetero-oligomer S100A8/A9 might also promote cancer cells migration and dissemination through regulation of tumoral microenvironment." (PMID 33801279, 2021). "In human cancer, monocytic MDSCs rather than polymorphonuclear MDSCs seem to be the major source of S100A8 although studies on S100A8 production by MDSC subsets have shown great variations by cancer type." (PMID 33146829, 2021). "In particular, S100A8, S100A9 and S100A12 are highly abundant proteins released by neutrophils and have been identified as important biomarkers in many inflammatory diseases and cancers." (PMID 33468080, 2021). "Secondly, elevated level of S100A8 and S100A9 observed in cancer and other inflammatory diseases." (PMID 34372836, 2021). "Second, at target genes where S100A8/A9 binds at both the enhancer and promoter regions, ONGs have higher transcriptional activity than noncancer genes and other classes of cancer genes." (PMID 33523865, 2021). "The distinction between cancer and noncancer genes is also observed when considering S100A8/A9 target sites showing the highest level of inducible binding upon transformation." (PMID 33523865, 2021). "The increased sensitivity of cancer cells to DOX chemotherapy upon S100A8 inhibition is not due to enhanced accumulation of DOX, but also due to enhanced intracellular free calcium ion content and overexpression of proapoptotic proteins." (PMID 33187385, 2020).
cancer (continued). "In the current study, we found that false-positive LNs contained a significant number of MDSC and expressed S100A8/A9, and that tissue S100A8/A9 expression in the absence of cancer cells can induce significant 18F-FDG uptake in the injected tissue." (PMID 32170086, 2020). "The intensity of 18F-FDG uptake was significantly increased by the S100A8/A9 injection., indicating that tissue S100A8/A9 expression in the absence of cancer cells can induce significant 18F-FDG uptake." (PMID 32170086, 2020). "Our results also revealed that the inactivation of YAP and the induction of S100A8/S100A9 could significantly increase the survival of cancer cells, which may also be a mechanism by which cancer cells overcome anoikis during metastasis." (PMID 31208368, 2019). "Our results contribute to the demonstration that S100A8 and S100A9 are critical for an efficient proinflammatory process but are also key actors of the development of many chronic inflammatory diseases and cancer." (PMID 29593718, 2018). "Neutrophils may be mobilized into liver premetastatic niches by S100A8 and S100A9 or chemokines and cytokines secreted by activated macrophages, endothelial cells, or cancer cells." (PMID 28969005, 2017). "Marked elevation for inflammatory signatures represented by S100a8 in the liver and lung but not in the heart and kidney confirmed that the former two organs are preferred targets of cancer-induced inflammation." (PMID 28388556, 2017). "Quantitative pyrosequencing analysis also showed that the S100A8 methylation level was decreased in cancer tissues (31.90%±13.31%) than that in the paired adjacent normal tissues (65.33%±3.64%, p<0.01)." (PMID 27462864, 2016). "S100A8 and S100A9 expression in cancer cells was critical for invasion by liver metastases." (PMID 27086923, 2016). "Moreover, given that metastases can and often do derive from other metastases, this makes the S100A8- and S100A9-mediated invasive capacity of cancer cells more ominous." (PMID 27086923, 2016). "In contrast, conditioned media from naIve monocytes/macrophages and granulocytes isolated from normal livers did not alter S100a8 and S100a9 mRNA expression in the cancer cells." (PMID 27086923, 2016). "When we constructed S100A8/A9-positive transfectants in S100A8/A9-negative (no S100A8/A9 protein complex) human carcinoma cells, transfection of S100A9 without S100A8 was unsuccessful and cells died." (PMID 26883112, 2016). "Moreover, S100A8 and S100A9 were found to be upregulated in defined parts of dysplasia/cancer regions and in the invasion nests in SCC sections." (PMID 25811984, 2015). "Therefore, there is a direct link between the expression of IL-17, CCL20, telomerase, S100A8, and S100A9 in the fibrotic condition and the progression towards cancer." (PMID 26273651, 2015). "The overexpression of S100A8 and S100A9 in cancer cells was also confirmed by immunohistochemistry." (PMID 25673070, 2015). "In addition, increased expression levels of S100A8 and S100A9 have been detected in various human cancers in recent years." (PMID 24083576, 2013). "Instead, S100A8/A9 expression increases protein phosphatase 2A (PP2A) activity, apparently through protein-protein interaction, which appears to be essential in modulating and restoring G2/M checkpoint signaling and reduction of carcinoma growth." (PMID 23874958, 2013). "KB cells were used as an in vitro model for gain-of-function study since this carcinoma line fails to express S100A8 and S100A9 mRNA and protein." (PMID 23874958, 2013). "Therefore exogenous or endogenous stimuli which induce S100A8 and S100A9 during developing cancers have the potential to exacerbate such disease states by augmenting the number or activation of MDSCs." (PMID 22946998, 2012). "Furthermore, S100A8 and MMPs are potential targets of SNO highlighting the multifaceted effects of NO signaling in cancer cell biology." (PMID 22971289, 2012).